CD4 (CD4 molecule)
Diseases named in the same sentence as CD4 in open-access papers (continued):
Sharing a sentence is not in itself a finding about the gene and the disease.
tumor (continued). "Largely, a high ratio of Treg to effector T cells within a tumor indicates a worse patient prognosis, and in some studies the frequency of Treg within the total CD4+ tumor-infiltrating lymphocyte population was found to be >60%." (PMID 31998326, 2019). "In summary, using scRNA-seq and data-driven computational approaches, the present study identifies an unsuspected diversity among tumor-responding CD4+ T cells." (PMID 31801070, 2019). "Rnf5−/− tumor-infiltrating CD4+ and CD8+ lymphocytes (TILs) also displayed greater effector function, including enhanced IFN-γ, TNF-α, and IL-2 production." (PMID 30940817, 2019). "This was also observed on NK cells, while NKG2D levels were found higher on tumor-infiltrating than on blood CD4 T cells." (PMID 30871626, 2019). "Mechanistically, administration of cDC1s increases tumor Ag-specific effector CD8+ T cells and recall responses of CD8+ and CD4+ T cells in the tdLN and the tumor short before the decrease in tumor growth becomes significant." (PMID 30961656, 2019). "In NSCLC, the number of CD8+ cells, CD4+ cells, T cells, and B cells are increased in tumor tissues as compared to normal lung tissues, among which the increase of B cells was found to be the most distinct." (PMID 30999966, 2019). "In one patient, we confirmed the direct recognition of autologous tumour cells by tumour-specific CD4+ T cells." (PMID 30718808, 2019). "A. muciniphila can cause IL-12 production and increase gut-tropic CD4+ T cells, which express the chemokine receptor CCR9 in tumor beds, tumor-draining lymph nodes, and mesenteric lymph nodes to exert an adjuvant effect on the anti-PD1 response." (PMID 31293523, 2019). "Compared to CD8 expression, relatively lower numbers of CD4+ cells were found in HNSCC tumor tissue." (PMID 31379843, 2019). "Previously we have reported that in tumor-bearing mice, CD4 depletion with an anti-CD4 depleting antibody (clone: GK5.1) enhances the proliferation of effector CD8+ T cells in the draining lymph node and results in potential anti-tumor immunity." (PMID 30696484, 2019). "It is worth looking into how MM-SC-DCs contribute to anti- tumor CD4 generation from naïve CD3 cells." (PMID 31164886, 2019). "This combined treatment increased substantially the number of CD8+, CD4+, and mature dendritic cells in the tumor milieu, while reducing the number of T regulatory cells and MDSC." (PMID 31662751, 2019). "Examination of pancreatic tissue from αKO/shB2m or αKO/CD80KO+shB2m mice that succumbed to tumor progression showed large tumors that were devoid of infiltrating CD4+ or CD8+ T cells." (PMID 31112530, 2019). "CD73 is expressed primarily by the cancer cells and the immune cells such as CD4+Foxp3+ regulatory T cells (Tregs), and myeloid-derived suppressor cells (MDSCs) that are recruited by the tumor." (PMID 30635578, 2019). "In parallel, migratory cDC2s that have captured the antigen also move from the tumor to dLN and activate CD4 T cells." (PMID 31143179, 2019). "On the other hand, chemokines orchestrate tumor homing of cells that are the major producers of IFNγ, such as Th1-polarized CD4+ T, CD8+ T cells, and NK cells." (PMID 30873179, 2019). "cDC1 are mainly associated with superior cross-presentation of tumor antigens to CD8+ T cells and polarization of CD4+ T cells into TH1 phenotype resulting in induction of anti-tumor immunity." (PMID 31736936, 2019). "Of interest, we observed an increase in the expression levels of GITR in the tumor-infiltrating lymphocytes, CD4+ and CD8+ T cells, two weeks after Delta-24-GREAT treatment." (PMID 31608328, 2019). "Antibody depletion experiments in 4T1-bearing mice treated with Nucl-TAP have shown that tumor inhibition was dependent on CD4+, CD8+, as well as on NK cells, the latter likely due to the reduced MHC class Ia expression resulting from TAP downregulation." (PMID 31434881, 2019).
tumor (continued). "CD4+ T cells exhibit anti-tumor effects and Th1 T cells are involved in the killing of tumor cells by secretion of cytokines that activate death receptors on tumor cells and induce epitopes spreading." (PMID 31555274, 2019). "Heat shock protein 90α (HSP90α) on the surface of TRAPs from malignant effusions of cancer patients and tumor cell lines stimulated CD4+ T cell production of IL-6 via a TLR2–MyD88–NF-κB signal cascade." (PMID 31300052, 2019). "Two infusions of several billion neoantigen-specific CD4+ tumor infiltrating lymphocytes led to a disease stabilization for more than 1 year." (PMID 31156634, 2019). "These tumours were characterised by the presence of abundant regulatory CD4+ T cells and CD8+ T cells co-expressing several inhibitory receptors (e.g., PD-1, Tim-3 and Lag-3)." (PMID 30413828, 2019). "Our flow cytometry‐based immune cell profiling included the quantitation of CD4+/CD8+ effector T cell ratios, exhaustion of CD8+ T cells, myeloid‐derived suppressor cells (MDSC), and tumor‐associated macrophages." (PMID 30885958, 2019). "We also investigated correlations between the levels of different CD4+ T cell subsets and the clinicopathologic features including disease stage and tumor budding." (PMID 31921188, 2019). "On this topic, strong correlations were found between increased tumor-infiltrating lymphocytes—such as CD4+ and CD8+ T cells—and the vascular normalization imposed by VEGF pathway inhibitors." (PMID 31156623, 2019). "Some studies have shown that microglia attract T-regulated lymphocytes to tumour sites, inhibit NK cell-mediated cytotoxicity, and block the functions of cytotoxic CD8+ T cells and the activation of tumour-reactive CD4+ T helper cells." (PMID 31729963, 2019). "The tumor content of CD4+ and Teff lymphocytes significantly increased while the frequency of cytotoxic CD8+ lymphocytes and Tregs remained unaltered (not shown)." (PMID 30655604, 2019). "Several clinical trials have shown that neoantigens can be recognized by CD8+ and CD4 + T cells in tumor tissue, and thus trigger an anti-tumor immune response in vivo." (PMID 31443694, 2019). "CD4+ T cells were selected for evaluation given their important role in producing IL-2 to support the optimization of tumor lysing CD8+ T cells." (PMID 31602007, 2019). "In total, CD4+ T cell responses to autologous tumour cells were detected in 16 out of 31 patients tested (52%), with a median frequency of 3.3% (considering only the highest value, when different assays were available for one individual patient)." (PMID 30718808, 2019). "In our study we observed differences in tumor-infiltrating CD4+ and CD8+ T cells following treatment with the combination, when analyzed by IHC and flow." (PMID 30670061, 2019). "We revealed that peripheral memory CD4+ T, memory CD8+ T, naïve CD4+ T, and CD4+ naïve/memory ratio were independent predictors for tumor response to SBRT in NSCLC lung metastases." (PMID 31080362, 2019). "We found that activated CD4+ T cells and M0 macrophages are found at high levels in tumor tissues, while neutrophil and monocyte levels are lower, and these results are consistent with previous studies." (PMID 31355524, 2019). "Another subpopulation of CD4+ cells known as regulatory T (Treg) cells that are involved in the dampening of antitumor activity in the tumor microenvironment." (PMID 31861720, 2019). "The tumor-infiltrating CD4+ T cell levels decreased significantly in the tumor-bearing IFNAR1-KO mice as compared to the WT tumor-bearing mice." (PMID 31228946, 2019). "Conversely, inhibition MHC-II antigen presentation by DCs to CD4+ T cells also promotes the development of anergic anti-tumor CD8+ T cells." (PMID 31379821, 2019). "In contrast, while antibody therapy only modestly increased IFN-γ-producing CD4+ T cells in the tumor, tritherapy significantly increased IFN-γ+, TNF-α + and IFN-γ + TNF-α + CD4+ T cells compared to all other treatments." (PMID 31747946, 2019).
tumor (continued). "It has been suggested that both IL-17+CD4+ and IL-17+CD8+ in tumor microenvironment can take a pathogenic role contributing to tumor progression." (PMID 31024835, 2019). "Like a double-edged sword radiation can also create an immunosuppressive environment through the recruitment of tumor associated macrophages (TAMs), myeloid derived suppressor cells (MDSCs), and CD3+CD4+CD25+Foxp3+ Tregs." (PMID 30895168, 2019). "Seven out of the eight patients with strong CD4 proliferation one month after radiotherapy were in T2–T4 stage based on the TNM tumor staging at the time of diagnosis." (PMID 31500214, 2019). "Consistent with the data of mRNA quantification, the Granzyme B expression in 4/21 ICR-CAR T cells was higher than in the control and 4/7 ICR-CAR T cells, especially in the CD4+ subset, after tumor cell stimulation." (PMID 31379876, 2019). "The functional role of CD4+ helper T cells in the tumour‐immune cell response is less understood compared to that of CD8+ T cells." (PMID 31485330, 2019). "Different operative procedures can affect T cell function in the tumor microenvironment by directly disrupting the function of CD4+ and CD8+ T cells." (PMID 31552179, 2019). "Efficient tumor elimination can be accomplished by the simultaneous induction of tumor specific CD4+ and CD8+ T cells." (PMID 31534520, 2019). "As such, future studies should investigate in detail the correlation between CD4 + T cells and the tumour microenvironment containing colonic microbiota." (PMID 31488881, 2019). "It is well established that complement components and their receptors C3aR and C5aR1 are expressed in not only myeloid and tumor cells but also CD4+ T lymphocytes." (PMID 31379815, 2019). "In a study of six patients with localized bladder cancer, those treated with ipilimumab had increased expression of ICOS on their CD4 T cells, both in the peripheral blood and the tumor." (PMID 31775882, 2019). "CD8 lymphocytes exerted their cytotoxic activity by eliminating tumor cells, while CD4 T lymphocytes sustained and maintained a CD8 T cell response by cytokine production." (PMID 30889935, 2019). "It has been demonstrated that in tumor microenvironment, tumor cells recruit immunosuppressive cells, such as CD4+ T cells, to disturb the cytotoxic functions of CD8+ T cells." (PMID 31570691, 2019). "Phosphorylation and acetylation profiles of STAT3 determine the differentiation and polarization of CD4+ Th17 cells that form the majority of tumor infiltrated T cells." (PMID 31861720, 2019). "The particularity of CTCL in the context of the implementation of immune checkpoint inhibitors relies on the fact that the tumor itself arises from CD4+ T cells, a population of lymphocytes responsible for the priming of cytotoxic response." (PMID 31554169, 2019). "HS-EVs were also shown to contain the chemokines CCL2, CCL3, CCL4, CCL5, and CCL20, which chemoattracted CD11c+ DCs and CD4+/CD8+ T cells into tumor tissues in vivo." (PMID 31680949, 2019). "CCK-8 results showed that 10 ng/ml of IL-24 stimulation slightly inhibited both peripheral and tumor-infiltrating CD4+ T cells proliferation (Tukey tests, P = 0.024 and P = 0.041, respectively)." (PMID 31921658, 2019). "Despite the anti-tumor potential of CD4+ T cells, disentangling their functional diversity has been the limiting factor for pre-clinical and clinical progress." (PMID 31801070, 2019). "Even though providing help is a major role for CD4+ T cells in anti-tumor immune responses, CD4+ T cells can contribute directly to regulation of the tumor microenvironment and to killing of cancer cells." (PMID 31379821, 2019). "Accordingly, double immunofluorescence on paraffin embedded tumours revealed that CD4+ and FOXP3+ T cells (Treg) were positive for LY6G6D staining, whereas CD8+ T lymphocytes did not." (PMID 30670049, 2019).
tumor (continued). "Transient depletion of CD4+ T cells results in tumor suppression and survival benefit in murine models; however, the tumor progression and recurrence still occur over more long-term monitoring of mice." (PMID 30696484, 2019). "We then assessed the cytotoxicity of PD-L1241-265-specific CD4+ T-cell line G1 against PD-L1-expressing tumor cell lines." (PMID 31221178, 2019). "The studies were also restricted to CD8+ T-cells only, leaving the landscape of spontaneous CD4+ T-cell responses to tumor neoepitopes unexplored." (PMID 31221207, 2019). "The human skin is an attractive anti-tumor vaccination site due to the vast network of dendritic cell (DC) subsets that carry antigens to the draining lymph nodes and stimulate tumor specific CD4+ and CD8+ T cells in." (PMID 31534520, 2019). "It has been known for some time that MHC class II-restricted (MHC-II) tumor antigens were capable of initiating CD4+ T cell responses critical for maintenance of anti-tumor immunity." (PMID 31379821, 2019). "Low concentration of IL-24 did not affect T-bet mRNA relative level in either peripheral or tumor-infiltrating CD4+ T cells (Tukey tests, P > 0.05)." (PMID 31921658, 2019). "Amazingly, TFP treatment induced PD-1 expression in the tumor-infiltrating CD4+ and CD8+ T cells from CT26 subcutaneous models." (PMID 31572198, 2019). "LX/IL-24-infected tumor cells increased infiltration of CD4+ T cells and CD8+ T cells in tumor sites, and the antitumor activity of the tumor vaccine modified with LX/IL-24 was dependent on CD8+ T cells." (PMID 31338417, 2019). "Cryo-thermal therapy induces a specific and durable anti-tumour memory immunity which dependents on antigen-specific CD4+ T cells." (PMID 31519961, 2019). "Re-stimulation of splenocytes from vaccinated mice with class II HER2 peptides led to increased IFN-γ production, suggesting the critical role of the anti-HER2 CD4+ Th1 immune response in mediating reduction in tumor burden with enhanced survival benefit." (PMID 31475002, 2019). "Immune status of a panel of seven subcutaneous syngeneic mouse tumor models was analysed by immunohistochemistry and flow cytometry with respect to their capacity to attract TILs, i.e. CD4+ and CD8a+ cells." (PMID 31754392, 2019). "For example, one study reported that high amounts of CCL21 recruit CD4+ LTi cells to tumors in a CCR7-dependent manner, which is associated with the formation of tumor-promoting lymphoid-like stroma in melanoma." (PMID 31507605, 2019). "It is conceivable, that CD4+ T cells facilitate dissemination of tumor cells exhibiting stem-cell character or an EMT phenotype." (PMID 30717704, 2019). "One study described TEM CD4+ T cells that were capable of tumor elimination and this was dependent on IFN-γ." (PMID 31379821, 2019). "Immunohistochemistry was applied to assess both the expression of membrane-bound PD-L1, and the number of CD4+ tumor-infiltrating lymphocytes (TILs) and CD8+ TILs." (PMID 30506460, 2019). "In a preclinical study, adoptive transfer of B. fragilis-reactive CD4+ T cells conferred enhanced tumor control and restored anti-CTLA-4 efficacy in GF mice." (PMID 30995949, 2019). "The anti-tumor response was postulated to be mediated by both CD4+ and CD8+ T cells given evidence of increased CD4+ and CD8+ IFN-γ producing cells." (PMID 30991681, 2019). "Single cell analysis revealed equal tumor cell killing by CD4+ and CD8+ CAR T cells, despite the former doing so following a longer conjunction period and delayed kinetics." (PMID 30875739, 2019). "Conversly, M1 TAMs stimulate anti-tumor CD4+ and CD8+ T cells response and also interact with NK cells that produce IFN-γ to amplify anti-tumor activity." (PMID 31500586, 2019). "Over the past decade, increasing evidence has suggested that the expansion of Tregs in tumor biopsies primarily reflects the (i)Tregs from CD4+CD25- naïve T cells educated by tumor cells." (PMID 30718502, 2019).
tumor (continued). "We focused on the activation of CD4+ cells, since there are several advantages of using tumor specific CD4+ T cells." (PMID 30956760, 2019). "Although our in vitro studies were designed to specifically address the response of CD8 T cells to CD3 redirection antibody engagement, it is highly likely that in vivo, CD4 T cells also play a role in tumor eradication." (PMID 31825302, 2019). "Compared to lung metastatic mice and normal mice, tumor cells that metastasized to the lungs caused a decrease in T cells, including CD8+ T cells and CD4+ T cells." (PMID 31022941, 2019). "CTLA-4, as a B7/CD28 family member, is involved in tumor immune evasion via down-regulation of CD4+ effector cells (Teff) and promotion of Treg cell activity." (PMID 31824865, 2019). "RT-PCR analysis and ELISA showed that hTRAPs from cancer patients and tumor cell lines efficiently induced human peripheral blood CD4+ T cells to express IL6 transcript and secrete IL-6." (PMID 31300052, 2019). "That is the case of toll-like receptor agonists, such as dextran-conjugated CpG oligodeoxynucleotides and double-stranded RNAs, whose application in vaccine formulations enhances tumor-specific TH1-polarized CD4+ T cells and CTL responses." (PMID 31156623, 2019). "As the tumor grade increased, the proportions of activated DCs, activated memory CD4+ T cells, M0 and M1 macrophages were gradually increased, whereas activated NK cells, monocytes, and resting DCs were decreased in cancer patients with higher grade tumors." (PMID 31762828, 2019). "Consistent with observations by other groups, our CD8-independent TCR from 19305DP provided strong tumor reactivity when it was expressed on CD4+ T cells in addition to CD8+ T cells." (PMID 30626427, 2019). "An NKp44 ligand was reported to be expressed on the surface of tumor or CD4+ T cell from HIV patients that was dependent on expression of HIV gp41." (PMID 31134055, 2019). "Based on our results, we believe that abrogating PIK3CA-AKT signaling in tumor cells attracts both CD4+ and CD8+ T cells to infiltrate the tumors." (PMID 31112530, 2019). "Patients with high tumor grade have an elevated percentage of CD4+CXCR5+ T-cells compared to those with low tumor grade." (PMID 31354634, 2019). "Interrogations of this limited therapeutic efficacy implicate tumour-induced CD4+CD25hiFoxp3+ T cells (Treg) in suppressing the development of effective anti-tumour immune responses." (PMID 30406375, 2019). "SM16 treatment of tumor-bearing mice resulted in reduced suppressive activity of splenic CD4+CD25+ cells." (PMID 31288845, 2019). "Depletion experiments indicated a critical role of NK cells and CD8+ T cells in the tumor suppression response to chemerin, while the depletion of CD4+ T regulatory cells enhanced tumor suppression." (PMID 31561459, 2019). "In animal models lapatinib promotes tumor infiltration by CD4 + CD8 + IFN-γ-producing T-cells through a Stat1 dependent pathway." (PMID 30922362, 2019). "The lowest numbers of CD4+ and CD8a+ cells were found in B16F10 (blue area), defined as a “cold” tumor, and intermediate T cell numbers were found in Renca and P815, although high CD4+ numbers were found in both models based on IHC score only." (PMID 31754392, 2019). "As seen in the B16-F10 model, most tumor-infiltrating CD4+ T cells expressed PD-1 in response to RTx, but combination with HHP vaccine did not enhance it further." (PMID 31555582, 2019). "This increased CD4+ Teff cell proliferation was also seen in the Panc02 tumor model and explains the altered Teff to Treg ratio by the tritherapy." (PMID 31747946, 2019). "Here, we explored the mechanistic aspects of TRAPs in the modulation of CD4+ T cells in the tumor microenvironment." (PMID 31300052, 2019). "Tumor-infiltrating T cells (TIT) presented a similar CD8/CD4 ratio, compared with the preinfusion T cells (baseline, BL), but the ratio from the spleen (SP) was relatively lower in these mice." (PMID 31488817, 2019).